ATR (ATR checkpoint kinase)
Diseases named in the same sentence as ATR in open-access papers (continued):
Sharing a sentence is not in itself a finding about the gene and the disease.
cancer (continued). "Inhibiting ATR activity impairs not only the DNA checkpoint response but also the overall mechanism of double-strand break (DSB) repair, making ATR an attractive target for cancer therapy." (PMID 40240755, 2025). "Here, we were able to show that neither impairment of nuclear actin polymerization nor ATR pharmacological inhibition (Fig. EV3B) had any impact on the frequency of NE rupture in migrating cancer cells." (PMID 40983686, 2025). "This is independent of both CHK1 and the TSC complex, and in cancer cells occurs through LSS regulation by ATR to increase cholesterol levels." (PMID 40514450, 2025). "The inhibition of key DDR components such as ATR is a strategy to increase the DNA damaging ability of current chemotherapies and radiation, thereby reducing the treatment resistant mechanism of DDR in cancers." (PMID 38227740, 2024). "Importantly, rearrangements found in cancers overlapping transcription-replication collision sites are detected in non-transformed cells and increase following treatment with ATM and ATR inhibitors." (PMID 38773641, 2024). "Interestingly, E7820-mediated double-strand breaks in DNA were increased in tumors with BRCA2 dysfunction, and knockdown of BRCA1/2 transcripts or knockout of ATM, ATR, or BAP1 sensitized cancer cells to E7820." (PMID 38789724, 2024). "Besides metabolic rewiring, we identify an increase in tetraploid cell frequency and DNA damage response as consistent hallmarks of acid-exposed cancer cells, supported by the activation of ATM and ATR signaling pathways." (PMID 38366255, 2024). "We have demonstrated that when looking at protons in isolation, cancer cells and HUVEC could be effectively radiosensitized by ATR inhibition, with increases in the sensitization enhancement ratio (SER) at SF2Gy." (PMID 39235982, 2024). "Compounds targeting these pathways may be active based on preclinical mechanistic cancer models and/or based on cancer patient data, including immune checkpoint blockade (anti-PD-1/PD-L1) and inhibitors of mTOR, PARP, ATR, EZH2, and HDAC." (PMID 39697230, 2024). "Similarly, ATR and CHK1/2 inhibitors hold promise as potential cancer therapies for the management of TNBC by targeting the DDR pathway and disrupting cell cycle regulation in cancer cells." (PMID 38539474, 2024). "Upon the occurrence of DNA single-strand breaks (DNA-SSBs), CHK1 is elicited and facilitates the coordination of the DDR through the ATR (ataxia telangiectasia rad3-related)–CHK1 pathway, as well as the activation of cell cycle checkpoint responses in cancer cells." (PMID 38473324, 2024). "Work from several groups has demonstrated the reliance on the ATR/Chk1 pathway in cancers that express little to no SLFN11, making these cancers more susceptible to ATR inhibition." (PMID 38791884, 2024). "In conclusion, our study suggests that the synthetically lethal effects of simultaneous impairment of ATR and POLA1 in cancer cells might represent a novel and promising approach for individualized cancer therapy." (PMID 39128273, 2024). "Moreover, T505 phosphorylation by CHK1 is necessary for efficient CHK1 activation by ATR, thereby driving dependence on the ATR/CHK1 signalling pathway, which is essential for the survival of cancer cells under high levels of DNA replication stress." (PMID 39050887, 2024). "In addition, APE1 is important for the activation of ATR-Chk1 DDR pathway under stress conditions (e.g., hydrogen peroxide and MMS) in human cancer cells, suggesting a conserved role of APE1 in the ATR-dependent DDR during evolution." (PMID 39112456, 2024). "Interestingly, we found that acid-exposed cancer cells exhibited a preferred response to inhibitors of ATM and ATR (vs. corresponding cells at physiological pHe)." (PMID 38366255, 2024). "Curiously, pharmacological inhibition of ATR sensitized cancer cells to 5-FU, too, but this occurred independent of homologous recombination." (PMID 35608750, 2023).
cancer (continued). "Alternatively, directly antagonizing the antiapoptotic cis- or mitochondrial ATR by inhibiting PP2A may reduce the apoptotic threshold of cancer cells, thereby promoting cancer cell death." (PMID 37511442, 2023). "As the MRN complex plays a crucial role in ATR and ATM activation in response to RS and DSBs, respectively, MRN complex inactivation may disturb the ATR/ATM-dependent anti-cancer barrier, leading to cancer progression." (PMID 37509263, 2023). "Moreover, we found that THZ531 synergically enhanced the cytotoxic activity of targeted DNA damage-inducing agents, such as Olaparib, ATR and ATM inhibitors, that are in use or being evaluated in clinical trials for other cancer types." (PMID 37599362, 2023). "In addition to promotion of DNA damage and cell death, inhibitor targeting proteins in DNA repair mechanism such as ATR and WEE1 also induce anti-tumor immune responses and sensitizes cancer cells to immunotherapy." (PMID 37087441, 2023). "To determine whether ATR overexpression could impact KRAS-driven cancer development, we focused on a cohort of LUAD patients from The Cancer Genome Atlas (TCGA) and sought to determine whether the expression level of ATR impacts overall survival (OS)." (PMID 37591859, 2023). "In ACP52C‐treated cancer cells, we also observed an increase in DNA strand breaks (SBs) and an upregulation of DNA damage responses (DDRs) markers, including γH2AX, as well as phosphorylated ATM, ATR, CHK1, and CHK2." (PMID 37845006, 2023). "Cis-ATR is not, as a matter of principle, mutagenic, but it allows cancer cells to evade apoptotic activation, which is particularly important for carcinogenesis." (PMID 37511442, 2023). "As ALT-dependent cancer cells are very selectively killed by ATR inhibitors, this inhibitor may be helpful in the treatment of ALT-positive cancers." (PMID 36860927, 2023). "Specifically, the clinical activity of ATR inhibition in PARP inhibitor (PARPi)-resistant tumors, including cancers with BRCA1/2 reversion mutations, has not been reported." (PMID 37277454, 2023). "Given the ability of ATR to protect cells from chronic RS induced by oncogenes and its potential role in regulating repriming, we sought to understand how ATR affects the RS response and determine the role of ATR-mediated RST during cancer development." (PMID 37591859, 2023). "The anti-cancer mechanisms of ciclopirox are complex and include the inhibition of Wnt/β-catenin, histone demethylases/Myc, VEGFR-3/ERK1/2, cyclin-dependent kinases, and mTORC1 and the induction of reactive oxygen species or activation of ATR/Chk." (PMID 37534217, 2023). "For example, we identified the driver gene set including ATR, COL4A2, and FLT1 in GBM individual TCGA‐12‐0821, and the Dscores of dysfunctional cancer hallmarks showed significant correlation with Escores of these cancer hallmarks (PCC = 0.86 and P = 1.25e‐08)." (PMID 37491836, 2023). "Given the emerging roles of ARID1A in the DNA damage response, accumulating evidence has enhanced our understanding of the biological role of ARID1A, offering new mechanisms for synthetic lethality-based targeting of ARID1A-inactivated cancers, such as inhibition of PARP and ATR." (PMID 36980292, 2023). "The clinical use of ATR/CHK1 inhibitors in the treatment of targeted cancer with or without combination therapy with chemotherapy and radiotherapy is supported by extensive preclinical data." (PMID 37511442, 2023). "We propose that by maintaining high Claspin levels, phosphorylation of the T505 site by CHK1 is required for efficient activation of CHK1 by ATR, thus driving the reliance on signalling through the ATR/CHK1 pathway required to survive high levels of DNA replication stress in cancer cells." (PMID 36240065, 2022).
cancer (continued). "Additionally, differences were observed in NR3C2, ATR, ALK, EPHB6, SPEN in intermediate cells (I-1 to I-8) relative to the cancer cells." (PMID 35951662, 2022). "To assess the cancer specificity of the replication defects caused by MTHFD2 inhibitors, we treated AML and nontumorigenic LCL cells with TH7299, TH9619, MTX or the ATR inhibitor VE-821." (PMID 35228749, 2022). "Since ATR is centered in the DDR pathway, SL involving ATR inhibition might solve the problem with undruggable cancers and resistance." (PMID 35458687, 2022). "Indeed, ATR and CHK1 inhibitors efficiently potentiate effects of DNA damaging agents in cancer cells." (PMID 35361811, 2022). "In our study, we report the co-occurrence of truncating mutations in ATM, CDK12, PTEN or ATR is present in 80% of MSS CRC with TMB-H and absent from TMB-L MSS cancers." (PMID 35740599, 2022). "Consequently, RS-inducing drugs including ATR and CHK1 inhibitors are used or evaluated as anti-cancer therapies." (PMID 35393546, 2022). "Numerous, promising preclinical and clinical studies suggest that ATM, ATR, CHK1, CHK2 and WEE1 inhibitors or modulators, alone or in combination with other therapeutics, could be potent therapeutic options for certain cancers, including TNBC." (PMID 36012478, 2022). "Since DDR can reduce the effectiveness of chemotherapy agents by activating checkpoints and triggering DNA repair pathways that result in increased tumor cell drug resistance and survival, it is not surprising that ATR is a therapeutic target in cancer cells." (PMID 35178190, 2022). "Moreover, PBRM1-defective cancer cells were sensitive to PARP and ATR inhibitors in preclinical models." (PMID 36138075, 2022). "Polθ is becoming a new target in cancer research because it demonstrates numerous synthetically lethal interactions with other DNA repair mechanisms, e.g., those involving PARP1, BRCA1/2, DNA-PK, ATR." (PMID 36613762, 2022). "The observation that ATR activity increases in response to CHK inhibition explains why many cancer cells can tolerate CHK1 monotherapy, possibly reflecting the ability of ATR to regulate origin firing, homologous-recombination repair, and/or nucleotide availability." (PMID 36381271, 2022). "Besides, applications of ATR/CHK1/WEE1 small-molecule inhibitors plus PARP inhibitors have been suggested, especially for cancer cells resistant to PARPi." (PMID 36253861, 2022). "Furthermore, pharmacological inhibition of ATR reversed TNBC cell resistance to topotecan, whereas MYC knockdown and JNK inhibition reduced cancer cell sensitivity." (PMID 35844787, 2022). "Because cancer cells with a high level of replication stress are particularly sensitive to ATR inhibition, we then treated the control and AE2 deletion MEC1 cells with ATR inhibitor Ceralasertib." (PMID 35778390, 2022). "Although a role for TopBP1 in ATR/Chk1 activation in normal cells is well established, the significance of TopBP1 overexpression in ATR/Chk1 activation in cancer cells expressing high levels of TopBP1 has not been investigated." (PMID 33556369, 2021). "Since most cancer cells are known to show dysfunction of the G1 checkpoints, ATR inhibition alone did not result in differences in cell cycle progression compared to the untreated non-irradiated control cells." (PMID 33546122, 2021). "Inhibitors of ATR, ATM and DNA-PK have been studied in many different cancer types." (PMID 34298632, 2021).
cancer (continued). "Belotecan monotherapy, a DNA-damaging agent, induced phospho-ATR (pATR) and phospho-Chk1 (pChk1) in SKpac-13 and SNU-119 cells, indicating that the DNA damage repair system is activated by the belotecan-induced DNA damage of cancer cells." (PMID 33513721, 2021). "ATR and CHK1 were identified as potential therapeutic targets for cancer." (PMID 34663432, 2021). "The results also support that simultaneous inhibition of BET and PARP, as well as ATR, especially in context of MYC amplified cancers such as this case, might result in a robust synthetic lethality in HR-reduced cancer cells." (PMID 34084283, 2021). "DDR genes including ATM, ATR, CHEK2, POLE, and POLQ could serve as potential biomarkers of ICI response, but their distinct and cancer-specific effects need to be investigated further." (PMID 34095878, 2021). "However, one preclinical study found that these cancers respond well to a combination of PARP inhibitors and ATR antagonists." (PMID 33299560, 2020). "ATR protein kinase has been proved as a key enzyme in the DNA damage response (DDR) which can limit the efficacy of cytotoxic chemotherapy agents and radiation during cancer treatment." (PMID 32815531, 2020). "We highlight our recent findings that PARP inhibition alone is cytostatic but not cytotoxic in ATM-deficient cancer cells and that the combination of a PARP inhibitor with an ATR (ATM, Rad3-related) inhibitor is required to induce cell death." (PMID 32183301, 2020). "Aberrant products of ATR/CHK1 pathway genes may contribute to the induction, promotion, and progression of cancer transformation." (PMID 33352723, 2020). "As APE2 has been shown in both BER and ATR pathways, it is interesting to test whether APE2 is directly involved in cancer immunotherapy in future studies." (PMID 32111912, 2020). "In this case, cancer cells would become refractory to the effects of ATR inhibition and resection factor abundance would not decrease." (PMID 32743550, 2020). "To test whether high expression levels of Cyclin E1 influenced DNA replication kinetics and sensitivity of cancer cells to ATR and WEE1 inhibitor, we aimed to downregulate Cyclin E1 expression in TNBC cancer cells." (PMID 33028815, 2020). "Challenges to this approach include: development of specific ATR inhibitors, delivery of the ATR inhibitors to achieve useful physiological concentrations in test subjects, and specificity in killing only cancer cells and not normal cells." (PMID 32426354, 2020). "Combined blockade of ATR and PARP is an effective therapeutic strategy for GBM, even in non-Myc PARPi-resistant GSCs, thus providing a much-needed therapeutic breakthrough for this deadly disease and possibly other BRCA1/2-wild-type or HR proficient cancers." (PMID 31266951, 2019). "Previously, cancer cells that express low-level Myc were considered independent of ATR, whereas Myc-driven cancer cells were characterized by increased replication stress and dependence on ATR to maintain genome stability." (PMID 31266951, 2019). "ATR has been a promising target for cancer therapy as proliferating cancer cells often have higher levels of replication stress and absent G1 checkpoints, making cancer cells reliant on ATR signaling." (PMID 30863489, 2019). "This analysis revealed that Claspin, Timeless, and CHK1 are overexpressed in a coordinated manner in these three cancers whereas the checkpoint sensors ATR, RAD17, and RAD9 are not." (PMID 30796221, 2019). "We also detected increased levels of CHK1 mRNAs, but not ATR, which is consistent with the levels observed in tumor samples and cancer cell lines." (PMID 30796221, 2019).
cancer (continued). "This is reminiscent of the correlation observed at the mRNA level in cancer patients and supports the view that Claspin, Timeless, and CHK1 are part of a functional module whose function is distinct from the ATR signaling pathway." (PMID 30796221, 2019). "This review describes the role of ATR and CHK1 and their validation as targets for cancer therapy, the development of inhibitors as chemo and radiosensitisers and as single agents exploiting the molecular pathology of cancer through to early clinical trials." (PMID 28448462, 2017). "ATR and CHK1 inhibitors have therefore been evaluated as sensitisers of ionising radiation (IR) and several cytotoxic drugs in a variety of models of human cancer." (PMID 28448462, 2017). "We propose that, similarly to the role of the ATR/CHK1 checkpoint, the cohesin complex, by preventive RS, may represent a liability of Myc driven cancers." (PMID 28749464, 2017). "In this study, we provided the compelling evidence that Cdc7-Dbf4 interacts with HCLK2-HSP90-Mre11 complex and phosphorylates HSP90-S164 to enhance ATR/ATM checkpoint signaling, HR DNA repair, and checkpoint recovery, which enhances replication stress tolerance for the survival of cancer cells." (PMID 29209046, 2017). "So far, the main mechanisms by which Roc-A inhibits cancer cell proliferation have been shown to be due to inhibition of protein synthesis initiation and induction of Cdc25A degradation by activation of the ATM/ATR check point pathway." (PMID 27340868, 2016). "Consequently, inhibition of ATR as the upstream kinase of CHK1 is expected to elicit additional and at least partly distinct effects than CHK1-inhibition when applied for cancer-therapeutic approaches." (PMID 26755646, 2016). "We found that the sensitivity of cancer cells to BO-1055 was increased following a combined treatment with the inhibitors of the DNA damage sensors ATM and ATR kinases, suggesting that both ATR and ATM are important in the repair of BO-1055-induced lesions in different fashions." (PMID 26208482, 2015). "We identified damaging mutations in ATR, BRCA1/2, MAP4K1, CUL3 and MAX, already reported in other cancer types but not described yet as mutated in PTC." (PMID 25803323, 2015). "In addition, the cancer genome atlas (TCGA) database was interrogated for alterations in: 1) ATM, MRE11A, RAD50 and NBN; 2) ATR, ATRIP and TOPBP1; and 3) 15 FA genes." (PMID 26438152, 2015). "In contrast, the co-amplification of ATR (located on human chromosome 3q22-q24) and TOPBP1 (located on human chromosome 3q22.1) in 11 carcinomas may increase ATR activity." (PMID 26438152, 2015). "In addition, mechanisms that increase replicative stress in cancer cells also appear to drive a reliance on the DDR, and ATR specifically, for survival." (PMID 25010037, 2014). "The observation that the role of BRCA1 in promotion of SCE following replication fork collapse is more profound in cells depleted of ATR provides the possibility of sensitizing cancer cells without functional of BRCA1 to PARP inhibitors by ATR inhibitors." (PMID 23388117, 2013). "Taken together, ATM-, ATR-, and NHEJ-dependent DNA damage response plays a central role in tumorigenesis and agents that disrupt this response may lead to the development of cancer." (PMID 18577246, 2008). "Indeed, it is reported that overexpression of Cdt1 can induce overt re-replication in cancer-derived cell lines, with activation of ATM/ATR checkpoint pathways." (PMID 17042960, 2006). "Next, we investigated whether a negative correlation between AEP and ATR levels could also be detected in these cancer cells." (PMID 40012043, 2025).